SDF2L1 (stromal cell derived factor 2 like 1)
Synonyms: AP000553.C22.4; OTTHUMT00000075032
Tractability: Antibody: UniProt predicts a signal peptide or a membrane-spanning region. PROTAC: ubiquitination databases record sites on it; its protein half-life has been measured.
Gene: Protein-coding gene on chromosome 22 (21,642,302 to 21,644,299, forward strand). Ensembl gene ENSG00000128228.
Subcellular location: Endoplasmic reticulum lumen
Gene Ontology:
Molecular function: misfolded protein binding; protein binding; ATPase binding; protein-folding chaperone binding
Biological process: protein refolding
Cellular component: endoplasmic reticulum; protein folding chaperone complex; endoplasmic reticulum chaperone complex; endoplasmic reticulum lumen; membrane
Genetic constraint (gnomAD): Loss-of-function variants: 18 observed, 13.54 expected, observed/expected ratio (o/e) 1.33, 90% interval 0.91 to 1.85. The synonymous counts are far from expectation, so gnomAD's model fits this gene poorly and the ratio says little. Missense variants: 263 observed, 260.52 expected, observed/expected ratio (o/e) 1.01, 90% interval 0.91 to 1.12. Synonymous variants: 161 observed, 125.71 expected, observed/expected ratio (o/e) 1.28, 90% interval 1.13 to 1.46.
Homologues: Orthologues: chimpanzee SDF2L1 (99% identical), macaque SDF2L1 (97% identical), dog SDF2L1 (96% identical), guinea pig SDF2L1 (92% identical), pig SDF2L1 (92% identical), rabbit SDF2L1 (90% identical), rat Sdf2l1 (90% identical), mouse Sdf2l1 (89% identical), tropical clawed frog sdf2l1 (67% identical), zebrafish sdf2l1 (64% identical), Drosophila melanogaster CG11999 (49% identical). Paralogues in human: SDF2 (61% identical), POMT2 (32% identical), POMT1 (29% identical).
Diseases named in the same sentence as SDF2L1 in open-access papers:
SDF2L1 is named in the same sentence as 23 diseases in open-access papers, as found by Europe PMC text mining. Sharing a sentence is not in itself a finding about the gene and the disease. The quoted sentences say what the papers report.
Insulin resistance (6 papers, 2019 to 2023). Increased resistance towards insulin, that is, diminished effectiveness of insulin in reducing blood glucose levels. "In diabetic individuals, insufficient Sdf2l1 induction was linked to insulin resistance and steatohepatitis development." (PMID 37928880, 2023). "In response to ongoing ER stress, inhibition of Sdf2l1 expression in the liver causes insulin resistance and raises triglyceride levels." (PMID 37928880, 2023). "In obesity and diabetes, impaired ER stress termination signals, including the down-regulation of Sdf2l1 that is caused by decreased insulin signaling, sustains ER stress and exacerbates insulin resistance, creating a vicious cycle." (PMID 30814508, 2019). "Suppression of hepatic Sdf2l1 expression reportedly results in insulin resistance with sustained ER stress in obese and diabetic db/db mice with leptin receptor mutation." (PMID 32978487, 2020). "Restoration of Sdf2l1 expression by administration of Ad-Sdf2l1 ameliorates insulin resistance and glucose tolerance in db/db mice." (PMID 33364514, 2020). "Insufficient expression of hepatic fibroblast growth factor 21 (FGF21) and stromal cell-derived factor 2 like 1 (Sdf2l1) reportedly leads to insulin resistance and hepatosteatosis in obesity and type 2 diabetes." (PMID 32978487, 2020). "It failed, however, to show full recovery of expression of downstream chaperones including Sdf2l1 and consequently insulin resistance, which urged us to restore the suppressed expression of Sdf2l1." (PMID 30814508, 2019). "In diabetic patients, insufficient induction of Sdf2l1 correlates with progression of insulin resistance and steatohepatitis." (PMID 30814508, 2019). "Suppression of Sdf2l1 expression in the liver results in insulin resistance and increases triglyceride content with sustained ER stress." (PMID 30814508, 2019). "In addition, among patients with diabetes, insufficient induction of Sdf2l1 has a positive correlation with the progression of insulin resistance and steatohepatitis." (PMID 36077090, 2022). "Moreover, expression of hepatic Sdf2l1 is decreased in obese and diabetic db/db mice and humans, and the suppression of hepatic Sdf2l1 expression results in insulin resistance and hepatic steatosis with a sustained ER stress." (PMID 33364514, 2020). "In the present study, we hypothesized that increases in hepatic FGF21 expression and circulating FGF21 levels precede diet-induced insulin resistance and hyperglycemia, which may be related to the increased expression of hepatic htr2a and Sdf2l1." (PMID 32978487, 2020). "Our results, however, demonstrated that hepatic Sdf2l1 expression was increased in insulin-resistant mice fed a high-fat diet, and that the suppression of increased hepatic Sdf2l1 expression induced by whey protein isolate improved insulin resistance in mice fed a high-fat diet." (PMID 32978487, 2020). "Thus, insufficient expression of hepatic FGF21 and Sdf2l1 may lead to insulin resistance and hepatosteatosis in obesity and type 2 diabetes." (PMID 32978487, 2020). "Thus, the increased expression of hepatic Sdf2l1 and FGF21 via htr2a might be related to insulin resistance in mice fed a high-fat diet." (PMID 32978487, 2020). "Based on our data, this may be partly through efficient induction of Sdf2l1 and BiP by XBP-1s, while over-expression of XBP-1s alone is not enough, because the translocation to the nucleus remains impaired without improving insulin resistance." (PMID 30814508, 2019).
diabetes (5 papers, 2019 to 2024). "In our investigation, we first established and successfully confirmed that the Sdf2l1 mutation in the diabetes prone CDs/y strain prevents altogether translation of the gene into SDF2L1." (PMID 36674879, 2023). "In the current study, we pursued the exploration of the pathophysiology of the disease in our model by focusing on the functional significance of the Sdf2l1 gene mutation, which we had recently detected in the diabetes-prone CDs/y strain." (PMID 36674879, 2023). "Therefore, failure to build an ER stress response in the liver may be a causal factor in obesity-related diabetes and nonalcoholic steatohepatitis, for which Sdf2l1 could serve as a therapeutic target and sensitive biomarker." (PMID 30814508, 2019). "We hypothesized that this deletion prevents expression of SDF2L1 and contributes to the pathophysiology of diabetes in CDs/y by impairing UPR, enhancing ER stress, and preventing CDs/y from secreting sufficient insulin upon demand." (PMID 36674879, 2023). "Therefore, the lower SDF2L1/sXBP1 ratio could be a much better biomarker than other ER stress-related genes, such as sXBP1 alone, to reflect not only ER stress but also ER stress response failure that leads to progression of diabetes-associated diseases in the liver." (PMID 30814508, 2019). "Moreover, in insulin resistant subjects with diabetes, despite elevated expression of sXBP1, the SDF2L1/sXBP1 ratio and the HSPA5/sXBP1 ratio were significantly lower." (PMID 30814508, 2019). "Similarly, in those with diabetes, sXBP1 was positively, but the SDF2L1/sXBP1 ratio was negatively, correlated with stage of NASH." (PMID 30814508, 2019). "We then investigated the role of Sdf2l1 in the development of diabetes and fatty liver disease." (PMID 30814508, 2019). "Here, Sasako and colleagues identify stromal cell-derived factor 2 like 1 (Sdf2l1) as a regulator of the ER stress response to feeding in the liver, and suggest that its downregulation may promote diabetes and hepatic steatosis in humans." (PMID 30814508, 2019). "Therefore, Sdf2l1 could become a potential therapeutic target and sensitive biomarker for diabetes and NAFLD." (PMID 36077090, 2022). "Thus, it remains to be investigated how lipid species in the liver, especially those isolated in microsomal fractions, are affected in response to feeding or chemically induced ER stress, and how such responses are disturbed by dys-regulation of Sdf2l1 or obesity-induced diabetes." (PMID 30814508, 2019). "Expression of SDF2L1 was significantly down-regulated in those with diabetes, whereas expression of the other genes was not." (PMID 30814508, 2019). "It was first revealed that expression of SDF2L1 was negatively correlated with glycemic control, and we focused on the presence or absence of diabetes thereafter." (PMID 30814508, 2019). "We then set out to determine the functional significance of the absence of the SDF2L1 protein in CDs/y and whether it was likely to be involved in the pathophysiology of diabetes in our model." (PMID 36674879, 2023).
nasopharyngeal carcinoma (4 papers, 2020 to 2023). A carcinoma arising from the nasopharyngeal epithelium. "All of these results revealed that SDF2L1 may play an inhibition role in the invasion and migration of nasopharyngeal carcinoma." (PMID 33134371, 2020). "Despite examining the link between the SDF2L1 gene and different cancer types, including Nasopharyngeal Carcinoma, its potential role as a CRC marker has not been acknowledged." (PMID 38134011, 2023). "The purpose of this study was to explore the relationship between stromal cell-derived factor 2-like 1 (SDF2L1) and nasopharyngeal carcinoma (NPC)." (PMID 33134371, 2020).
breast cancer (3 papers, 2015 to 2021). A primary or metastatic malignant neoplasm involving the breast. "SDF2L1 is an independent prognostic indicator in breast cancer, and the reduced level of SDF2L1 is related to poor clinical outcomes." (PMID 34745201, 2021). "Recently, studies reported that SDF2L1 may act as a tumor suppressor gene and play an important role in a variety of cancers, such as breast cancer and ovarian cancer." (PMID 33134371, 2020). "Sdf4 is a member of the stromal cell derived factor (SDFs) family and functionally classified as a chemokine; SDF-2, SDF-4 and SDF-5 are expressed in mammary tumor tissues and cells and a reduced level of SDF-2, SDF2-L1 and SDF-4 are associated with a poor clinical outcome." (PMID 26681200, 2015).
Obesity (3 papers, 2019 to 2022). Accumulation of substantial excess body fat. "Thus, Sdf2l1 is expected to be a therapeutic target and a sensitive biomarker in obesity-associated diseases." (PMID 30814508, 2019).
Hyperglycemia (2 papers, 2020). An increased concentration of glucose in the blood. "In summary, the present findings suggest that expression of the hepatic htr2b is increased in young diabetic db/db mice and KKAy mice, and pharmacologic inhibition of htr2b ameliorates the hyperglycemia and altered expression of hepatic FGF21, Sdf2l1 and htr2a in these mice." (PMID 33364514, 2020).
Glucose intolerance (1 paper, 2019). Glucose intolerance (GI) can be defined as dysglycemia that comprises both prediabetes and diabetes. "In obese and diabetic mice, Sdf2l1 is downregulated due to decreased levels of nuclear XBP-1s, whereas restoration of Sdf2l1 expression ameliorates glucose intolerance and fatty liver with decreased ER stress." (PMID 30814508, 2019).
ovarian carcinoma (1 paper, 2020). A malignant neoplasm originating from the surface ovarian epithelium. "Furthermore, a meta-analysis found that the expression levels of SDF2L1 were correlated with poor prognosis of ovarian cancer patients." (PMID 33134371, 2020). "The low expression of SDF2L1 has been observed in breast and ovarian cancer." (PMID 33134371, 2020).
serous ovarian cancer (1 paper, 2021). "The expression profiles of SDF2L1, PPP1R12A, and PRKG1 were associated with the clinical outcomes of high-grade serous ovarian cancer." (PMID 34745201, 2021).
steatosis (1 paper, 2022). Increased lipid within the cytoplasm of cells. "Our data revealed that Sdf2l1 within the St13-Sdf2l1 complex plays a protective role in acinar injury and steatosis through regulation of the AA pathway." (PMID 35562743, 2022). "In CP, St13 plays a protective role in acinar steatosis by binding Sdf2l1." (PMID 35562743, 2022).
cancer (3 papers, 2020 to 2023). A tumor composed of atypical neoplastic, often pleomorphic cells that invade other tissues. "Previous studies have shown that SDF2L1 is closely related to endoplasmic reticulum stress which is involved in the occurrence and development of a variety of diseases, especially cancers." (PMID 33134371, 2020). "In conclusion, SDF2L1 may act as a cancer suppressor gene, play a crucial role in the occurrence and development of NPC, and be a new therapeutic target or prognostic indicator for NPC." (PMID 33134371, 2020).
tumor (2 papers, 2020 to 2023). "Our research directly indicated that SDF2L1 as a tumor suppressor gene may play an important role in NPC occurrence and development." (PMID 33134371, 2020). "The top 5 proteins exclusively detected in tumor in ≥ 90% of the cases included CD68 (a macrophage marker), Optineurin (OPTN), Nuclear receptor coactivator 5 (NCOA5), RAP1GDS1 (Rap1 GTPase-GDP dissociation stimulator 1) and Stromal cell derived factor 2 like 1 (SDF2L1)." (PMID 36508875, 2023).
SDF2L1 also shares sentences with these, for which no sentence is quoted: Hepatic steatosis (4 papers); Hyperinsulinemia (2); metabolic disorders (2); chronic nasopharyngitis (1); colon cancer (1); gastric cancer (1); melanoma (1); nonalcoholic steatohepatitis (1); prostate carcinoma (1); Sepsis (1); type 2 diabetes (1).